EIF4E (eukaryotic translation initiation factor 4E)
Diseases named in the same sentence as EIF4E in open-access papers (continued):
Sharing a sentence is not in itself a finding about the gene and the disease.
melanoma (continued). "Our results indicate that EPO exerts a powerful stimulatory effect on cell proliferation and de novo protein synthesis in melanoma cells through activation of the initiation factor eIF4E." (PMID 28415825, 2017). "Using eIF4E siRNAs, we observed that downregulation of eIF4E expression in B16 melanoma cells can profoundly reverse the EPO-induced increase in melanoma cell proliferation, suggesting that EPO-mediated melanoma tumor cell growth is eIF4E-dependent." (PMID 28415825, 2017). "Meanwhile, it has been reported that eIF4E negatively regulated the expression of E-cadherin in melanoma." (PMID 27907907, 2016). "Furthermore, recent work in melanoma suggests a role for eIF4E phosphorylation in cellular phenotypic switching, with consequences for local immune responses." (PMID 39145446, 2024). "Moreover, phopsho-eIF4E levels were found to correlate negatively with MART-1 expression in melanoma biopsies." (PMID 39199632, 2024). "In a BRAFV600; PTEN KO mouse melanoma model in which eIF4E cannot be phosphorylated (eIF4EKI), they showed an increase in the secretion of many cytokines linked with the expansion, recruitment (such as CCL2, CCL12, and CCL5), and function (such as MMP-9) of immunosuppressive cells such as MDSCs." (PMID 35432344, 2022). "While PD-L1 may be regulated at the transcriptional level, recent data highlighted a translational control through the translation complex eIF4E in melanoma." (PMID 35432344, 2022). "We detected quite a pronounced expression level of eIF4E in both the melanoma cell lines." (PMID 33916175, 2021). "It was shown that interfering with the function of the eIF4F complex resulted in a decreased expression of PDL-1 either after interfering with translation of STAT1 leading to a lower transcription of PDL-1, or via interfering with eIF4E phosphorylation and activity, in melanoma or liver cancer." (PMID 32151059, 2020). "Increased phospho-eIF4E levels is an independent prognostic factor in astrocytomas, NSCLC, and nasopharyngeal carcinoma, while also being associated with disease progression in melanoma and prostate cancer." (PMID 32517051, 2020). "This recent study hence proposes that MDSC-specific eIF4E phosphorylation may be the major determinant of tumoral immunosuppression in melanoma." (PMID 32731503, 2020). "Thus, agents that repress the eIF4E-eIF4G interaction hold the promise of inhibiting high-risk melanomas that are inherently drug resistant, such as NRAS-mutant melanomas, or those with acquired resistance to therapy." (PMID 32517051, 2020). "Therefore, by demonstrating that CXCR7 is capable of accelerating HIF-1α translation by promoting Src-mediated eIF4E phosphorylation, our findings raise the possibility of interfering with this axis as clinical therapeutics for melanoma patients." (PMID 30804329, 2019). "Therefore, our findings demonstrate that CXCR7 promotes HIF-1α translation in melanoma by facilitating Src-mediated eIF4E phosphorylation." (PMID 30804329, 2019). "Further, the alterations in major components of the mTOR pathway like loss of function of PTEN, PI3K amplification/mutation and over-expression of S6K1, 4EBP1, eIF4E and AKT have been reported to be associated with many types of cancers, particularly in melanoma and glioblastama." (PMID 28587194, 2017). "Knock-down of eIF4E significantly repressed the proliferation of a subset of melanoma cell lines." (PMID 26767073, 2016). "eIF4E is overexpressed in a panel of melanoma cell lines, compared to immortalized melanocytes." (PMID 26767073, 2016). "Further, the persistent formation of the eIF4F complex, comprising the eIF4E cap-binding protein, the eIF4G scaffolding protein, and the eIF4A RNA helicase, was associated with resistance to BRAFi, MEKi, and BRAFi/MEKi combination in BRAFV600E melanoma, colon, and thyroid cancer cells." (PMID 37834284, 2023).
melanoma (continued). "High IGF2BP3 expression enhanced melanoma cell proliferation by accelerating the degradation of EIF4E-BP2 mRNA and promoting the translation of EIF4E." (PMID 35676262, 2022). "For example, in cancer models, Salubrinal combined with 4E1RCat (a dual inhibitor of eIF4E:4E-BP1 and eIF4E:eIF4G) decreased protein synthesis in melanoma cells and impeded tumor growth in mice." (PMID 33652720, 2021). "A recent study reported that inhibiting eIF4E might be a viable therapeutic approach to overcome resistance to vemurafenib, BRAF inhibitor, in melanoma." (PMID 28417568, 2017). "Moreover, in BRAF V600E melanoma cell lines, vemurafenib inhibits 4E-BP1 phosphorylation, thus promoting its binding to eIF4E." (PMID 26767073, 2016). "This assumption is further promoted by the finding that only eIF-4A1 but none of the other group 4 translation factors (eIF-4E, eIF-4B, eIF-4G, eIF-4A2) was significantly upregulated in melanoma cells as compared to normal melanocytes." (PMID 12085193, 2002). "Recent studies have focussed on the role of the factors eIF-4E and eIF-2α in malignant cell transformation; no data were available on melanoma cells." (PMID 12085193, 2002). "Interestingly, the member EIF4E of the family is reported to increase the level of Cyclin D1 protein in vitro, while other members (components of the EIF3 complex, in particular), have been correlated to human cancer, and human melanoma." (PMID 31921654, 2019). "Importantly, our studies demonstrate, for what we believe to be the first time that stimulation of melanoma cells with therapeutic concentrations of EPO induced an increase in phosphorylation, and therefore activation of the translational regulatory protein eIF4E." (PMID 28415825, 2017). "In the phase I clinical trial, LY2275796 was tested in multiple advanced cancers including melanoma, and while administration of LY2275796 at 1000 mg/kg was well-tolerated and was effective at decreasing overall eIF4E levels in tissues, no tumor response was observed." (PMID 32517051, 2020).
lymphoma (34 papers, 2007 to 2024). A malignant (clonal) proliferation of B- lymphocytes or T- lymphocytes which involves the lymph nodes, bone marrow and/or extranodal sites. "An association between increased eIF4E expression and cellular transformation is also seen in several tumors including that of the breast, bladder, colon, head and neck, lymphoma, lung, and thyroid." (PMID 24504069, 2014). "For instance, RIP-Seq analysis in lymphoma cells indicated that nuclear eIF4E binds over 3000 mRNAs that encode proteins acting in lymphoma-sustaining pathways such as B-cell receptor signaling (Bcl2, Bcl6) and DNA methylation/epigenetic regulation (DNMT1, DNMT3A, HDAC1)." (PMID 30455716, 2018). "To address whether inhibitors of translation elongation could also synergize with DNA damaging agents (e.g. Dxr), we tested the potential of four elongation inhibitors to modulate chemosensitivity in the Eμ-myc model harboring lymphomas with loss of Pten or Tsc2 or over-expressing Bcl-2 or eIF4E." (PMID 19412536, 2009). "Not only does eIF4E overexpression exhibit oncogenesis in vitro, but multiple-fold eIF4E overexpression has been documented in various cancers, including breast, lung, leukemias, lymphoma, colon, and head and neck squamous cell carcinoma." (PMID 39409166, 2024). "Silvestrol has been shown to enhance sensitivity to doxorubicin by inducing apoptosis in mouse lymphoma models driven by PTEN inactivation or eIF4E overexpression." (PMID 37874652, 2023). "Rapamycin reverses the chemoresistance in AKT-overexpressing lymphomas in a murine lymphoma model via disruption of the AKT/mTOR/eIF4E signaling pathway by inhibiting mTOR activity." (PMID 35111368, 2022). "In vitro evidence suggests that increased MCM3AP-AS1 controls the sensitivity of lymphoma cells to doxorubicin by regulating the miR-15a/EIF4E pathway." (PMID 34692706, 2021). "Many data suggest that eIF4F, a translation initiation factor composed of eIF4E, eIF4A and eIF4G, plays an important role in maintaining the translation of a variety of important leukemia and lymphoma oncogenes and transcription factors." (PMID 33673851, 2021). "Animal experiments have demonstrated that downregulation of MCM3AP-AS1 contributes to the expression of miR-15a and PARP, whereas it inhibits the expression of Mcl-1 and EIF4E in lymphoma." (PMID 34692706, 2021). "Transgenic mice overexpressing eiF4E develop lymphomas, angiosarcomas, lung carcinomas and hepatomas." (PMID 28415825, 2017). "For example, aberrant activation of eukaryotic translation initiation factor 4E (eIF4E) has been shown to be critical for tumorigenesis of a number of cancers including lymphomas, angiosarcomas, lung carcinomas, and hepatomas." (PMID 26848623, 2016). "As the association of 4E-BP1 and eIF4G with eIF4E is mutually exclusive, the EtOH-triggered accumulation in 4E-BP1-eIF4E complexes appropriately decreased eIF4G-eIF4E interactions in both lymphoma cell lines." (PMID 25849580, 2015). "We demonstrate here that the cap bound fraction from lymphoma cells was enriched with eIF4G and eIF4E indicating that lymphoma cells exist in an activated translational state." (PMID 25839159, 2015). "Overall, these data suggest that high levels of eIF4E along with hyper-phosphorylated 4E-BP1 exist in the lymphoma cells and contribute in the formation of active eIF4F complex." (PMID 25839159, 2015). "Overall, these data demonstrate that the cap bound fraction from lymphoma cells was enriched with eIF4G, eIF4E and eIF4A, demonstrating that aggressive lymphoma B cells exist in a translationally activated state." (PMID 25839159, 2015). "In the Eu-myc mouse lymphoma model, expression of wild-type eIF4E, the phosphomimetic eIF4E-S209D mutant, or activation of the eIF4E kinase Mnk1 all accelerated tumor development." (PMID 25923732, 2015). "In PTEN-null mouse lymphoma and prostate cancer models, disruption of eIF4E phosphorylation abrogates tumor development." (PMID 25923732, 2015).
lymphoma (continued). "GAS5 was enriched with eukaryotic translation initiation factor-4E (eIF4E) in an RNA-immunoprecipitation assay using lymphoma cell lines." (PMID 25197831, 2014). "The administration of silvestrol, an inhibitor of eIF4E, was able to reverse pim2-mediated rapamycin resistance in human lymphoma cells and in vivo." (PMID 24860787, 2014). "RNA-IP results showed that GAS5 was enriched with eIF4E as compared with IgG control in all the lymphoma cell lines, Jeko, Mino, Granta and JVM2, as well as in HEK-293T cells." (PMID 25197831, 2014). "Enhanced eIF4E phosphorylation has been observed in various solid tumors and lymphomas, and p-eIF4E overexpression is correlated with poor prognosis or recurrence, metastases in human tumors." (PMID 24551240, 2014). "Studies with eIF4E expressing transgenic mice have revealed a marked increase in the incidence of various cancers including lymphomas, lung adenocarcinomas, angiosarcomas, and hepatomas." (PMID 24504069, 2014). "In an elegant study, a mouse model in which lymphomas generated from Eμ-Myc transgenic HSCs (hematopoietic stem cells) were transfected with wild-type eIF4E and eIF4E-mutants, was used to investigate their effects on oncogenicity." (PMID 22392765, 2012). "As observed with Pten+/−Eμ-Myc lymphomas, treatment of mice bearing Eμ-Myc/eIF4E lymphomas with any of the elongation inhibitors alone was not effective in inducing remissions." (PMID 19412536, 2009). "eIF4E is oncogenic in vivo and in Eμ-Myc lymphomas over-expressing this factor, rapamycin is unable to modulate chemosensitivity whereas silvestrol can." (PMID 19412536, 2009). "These lymphomas over-express eIF4E and are resistant to Dxr+Rap combination treatment, but sensitive to the combination of Dxr and silvestrol, an eIF4A activity modulator." (PMID 19412536, 2009). "To assess the efficacy of translation elongation inhibitors on Rap-resistant lymphomas, we examined the activity of these compounds on Eμ-Myc/eIF4E lymphomas." (PMID 19412536, 2009). "eIF4E is also oncogenic in vivo, as eIF4E promotes the development of lymphomas and several types of carcinomas in mice." (PMID 17311107, 2007). "Moreover, eIF4E overexpressing-lymphomas are relatively resistant to chemotherapy demonstrating that dysregulated mRNA translation can influence both tumor development and treatment responses." (PMID 32924027, 2020). "Perhaps the most direct evidence to support the role of eIF4E phosphorylation in cancer was obtained from a series of eIF4E or MNK1/2 mutants which were used to test their contribution to the lymphoma tumorigenesis in the Eμ-Myc transgenic mouse lymphoma model." (PMID 33148274, 2020). "Moreover the 4E-BP1/eIF4E axis was reported as a key event in Myc lymphomagenesis since 4E-BP1-dependent inhibition of eIF4E activity impedes Myc-driven lymphomas." (PMID 28915586, 2017). "The presence of eIF4E expression by IHC should be further evaluated in trials of dual mTOR inhibitors to learn whether the expression predicts response to these agents in lymphoma patients." (PMID 25839159, 2015). "To explore whether GAS5 plays a role in regulating protein translation in lymphoma cells, we first detected the association of GAS5 with the translation initiation factor eIF4E since the initiation of translation is a key step in translation regulation." (PMID 25197831, 2014). "Consequently, drugs targeting eIF4E and other translation factors have received increased attention as possible therapeutic approaches in leukemia and lymphoma." (PMID 24586420, 2014). "Mnk1- and eIF4E-expressing lymphomas showed low levels of apoptosis compared to control tumours." (PMID 22392765, 2012). "Further, a lymphoma mouse model showed that eIF4E overexpressing mice developed more lymphomas." (PMID 20049173, 2009).
lymphoma (continued). "Eukaryotic initiation factor 4E (eIF4E), which together with eukaryotic initiation factor 4G (eIF4G) and eukaryotic initiation factor 4A (eIF4A) form the cap-binding complex, is frequently overexpressed in human cancer and can cooperate with the Myc oncogene in an experimental lymphoma model." (PMID 24586420, 2014). "In lymphoma cells, lncRNAs exist that can regulate the translation of the MYC specific mRNA in cooperation with the eukaryotic translation initiation factor 4E (eIF4E)." (PMID 33134177, 2020). "Interestingly, ribavirin cooperated with an HSP90 inhibitor to suppress tumor growth (patient-derived lymphoma xenograft or xenografts of established double/triple-hit B-cell lines) potentially since HSP90 binds to eIF4E and may be required to maintain or enhance its activity." (PMID 32924027, 2020). "In another study, in the context of a T-cell specific PTEN-null lymphoma model, deletion of MNK1/2 resulted in delayed onset of lymphoma, with a complete abolishment of eIF4E phosphorylation." (PMID 32517051, 2020). "This agent extended survival when combined with chemotherapy in both the Eμ-MYC/eIF4E and Eμ-MYC/PTEN+/− lymphoma models, in which MYC and mTOR are deregulated to drive lymphoma onset." (PMID 29799508, 2018). "Our data suggest that low 4EBP1 expression and/or high eIF4E expression might be negative predictive markers for asTORi efficacy in lymphoma." (PMID 24586420, 2014). "Interestingly, both pim2- and AKT-expressing lymphomas relied on cap-dependent translation, and the rate-limiting factor for this translation is the activation of the cap-binding protein by phosphorylation of its inhibitor 4E-BP1, which can be further enhanced by direct eIF4E phosphorylation." (PMID 24860787, 2014).
autism (30 papers, 2011 to 2026). Persistent deficits in social interaction and communication and interaction as well as a markedly restricted repertoire of activity and interest as well as repetitive patterns of behavior. "The findings reveal that oxytocin plays a pivotal role in modulating the functional state of microglia during the development of autism, particularly in individuals associated with eIF4E mutation." (PMID 39557567, 2024). "Overexpression of the eukaryotic initiation factor 4E (eIF4E) gene has been associated with excessive stereotypic behaviors and reduced sociability, which manifest as autism-like social cognitive deficits." (PMID 39557567, 2024). "We previously showed that the autism-related pathogenic effects of exaggerated cap-dependent translation on mouse brain physiology and behavior can be reversed by targeting “eIF4E-sensitive” mRNAs such as Nlgn1." (PMID 37293130, 2023). "We then showed that ADNP interacts with the autism-linked protein eukaryotic translation initiation factor 4E (eIF4E) and further regulates it expression in males only." (PMID 32072336, 2020). "Mutations in EIF4E have also been implicated as a cause of autism in humans, and enhanced eIF4E activity has been associated with autism-like phenotypes in animal models." (PMID 31314787, 2019). "The most direct evidence comes from monogenic, syndromic forms of autism, many of which are caused by lost or reduced function in genes, including eIF4E, FMR1, PTEN, NF1, TSC1, TSC2 and PRKCB1, that negatively regulate the pathway or its subsystems." (PMID 31548888, 2019). "For example, mutations in CHD4 (OMIM # 617159) cause neurodevelopmental delays, chromatin remodelers have been associated with cognition, Eif4e has been tightly linked with autism and autophagy with autism, brain degeneration and schizophrenia." (PMID 30534048, 2018). "Accordingly, mutations in EIF4G1 have been recognized to associate with PD, and deregulation of EIF4E activity seems to increase susceptibility to autism (AUTS19)." (PMID 28798667, 2017). "Compelling evidence suggests a link between exaggerated protein synthesis and ASD, and autism-related deficits have been recently associated to dysregulation of eIF4E-dependent translational control." (PMID 28809922, 2017). "eIF4E is considered to be a proto-oncogene, since its overexpression causes tumorigenic transformation of fibroblasts, and high levels of eIF4E have also been implicated in autism-like behaviors." (PMID 25463438, 2015). "Notably, within the core network, MTOR (with a gene score of 2 and identified as a syndromic gene) and EIF4E (with a score of 3) are considered autism susceptibility genes." (PMID 39858558, 2024). "However, the precise mechanisms by which eIF4E overexpression insufficiently induces these autism-like behaviors and the specific brain regions implicated remain insufficiently understood." (PMID 39557567, 2024). "In addition, mutations in the downstream mTOR target eukaryotic translation initiation factor 4E (eIF4E) have also been associated with autism." (PMID 24379984, 2013). "Recently novel association of the eIF4E protein component of this family with autism was reported." (PMID 21347362, 2011). "Mutations in the eIF4E promoter are present in some individuals with autism, and eIF4EBP2 knockout and eIF4E-overexpressing mice exhibit autism-like phenotypes, strengthening the hypothesis that disruptions in mTOR-dependent protein synthesis contribute to autism pathology." (PMID 29691724, 2018). "Notably, one pioneering study has identified a mutation in the EIF4E promoter in autism families, implying that deregulation of downstream mTOR signaling (eIF4E) could be a novel mechanism for ASDs." (PMID 23533374, 2013). "Pharmacologically inhibiting the interaction between eIF4G1/eIF4E suppressed translation and has been used to affect spine morphology in autism mouse models." (PMID 40931164, 2026).